STAT1 (signal transducer and activator of transcription 1)
Diseases named in the same sentence as STAT1 in open-access papers (continued):
Sharing a sentence is not in itself a finding about the gene and the disease.
tumor (continued). "In tumour IFN-driven resistance, stimulation of cancer cells by IFN-γ leads to the nuclear translocation of signal transducer and activator of transcription 1 (STAT1)." (PMID 33257838, 2021). "Subcutaneous CRPC xenograft tumor growth was also reduced by single-agent ENZ treatment and single-agent FLUD, a specific STAT1 antagonist, treatment; but much superior effect was elicited by the combination treatment of ENZ + FLUD." (PMID 34746227, 2021). "The results showed that the expression of STAT1, STAT2, STAT3, STAT5A, and STAT6 increased with increasing tumor grades." (PMID 34276757, 2021). "Collectively, these data suggest the critical role of STAT1 in the early events of CAC, as it prevents the development of a favorable inflammatory microenvironment for tumor growth." (PMID 34299314, 2021). "We have observed significant upregulation of IFNG, JAK3, STAT1, and STAT2 in tumor compared to normal samples." (PMID 33980865, 2021). "Therefore, Stat1 may participate in some unidentified mechanisms to regulate tumor progression." (PMID 34685622, 2021). "The aim of this study was to investigate the irradiation effect on IFNγ-mediated STAT1 and STAT3 phosphorylation and genes expression such as PD-L1 and anti-apoptosis genes in EGFR-positive tumor cells to augment CD8+ T cells cytotoxicity against NSCLC." (PMID 34685495, 2021). "However, recent research found that OvCa patients with high intratumoral STAT1 activation exhibited poor prognosis compared with patients with low STAT1 activation via immunohistochemical analysis, indicating STAT1 may have a dual role in tumor development." (PMID 34248988, 2021). "As reported, JAK/STAT1, JAK/STAT3, and JAK/STAT5 are three classic pathways that play a crucial role in tumor progression." (PMID 35047409, 2021). "STAT1 expression is stimulated by IFNγ and leads to the expression of MHC-II at the tumor cells surface which are molecules presenting tumoral antigens to the host immune system." (PMID 33691728, 2021). "Collectively, our western blot results revealed that miR-195-5p upregulation reduced the protein expression levels of p-p38, p-JAK2 and p-STAT1 in PTC cells and tumor xenografts, CircRNA NRIP1 overexpression reversed those effects." (PMID 34689819, 2021). "After phosphorylation by JAK1/2, they promote tumor immunogenicity by upregulating MHC and immune checkpoint proteins (such as PD-L1 and B7-1) through STAT1 signaling of transcription factors." (PMID 34838003, 2021). "IFN-induced STAT1 can subsequently activate chemokines, such as CXCL9, CXCL10, and CXCL11, which can recruit more CD8+ T cells to provide anti-tumor immunity." (PMID 34282238, 2021). "We investigated JAK1 and STAT1 protein expression levels in macrophages from CTRL and Co-CM1 groups and found that their expression was inhibited in macrophages co-cultured with tumor cells." (PMID 33937269, 2021). "With increasing levels of tumor PD-L1, the expression of transcription factors for Th1, Th2, or M1 macrophages, including NFKB1, GATA3, HIF1A, STAT4, TBX21, IRF8, and STAT1, was downregulated." (PMID 33754038, 2021). "Of note, STAT1+IRF1+ TAM have been observed in tumor-bearing mice with DICER conditional deletion and resulted in tumor inhibition by recruitment of activated CTL." (PMID 34220848, 2021). "The refined six gene tumor immune signature (IDO1, CXCL10, CXCL9, HLA-DRA, STAT1, IFNG) was carried on a sample of cases representative of the Sema4D HIS subtypes using basic nSolver analysis." (PMID 33776991, 2021). "IHC validation on tumor samples showed an activation of the FGFR2 downstream targets AKT, p44/p42 MAPK, p38 MAPK, STAT1, and STAT3." (PMID 34480077, 2021). "Through a systems medicine approach, it was determined that hub biomolecules, AR, GATA2, miR-124, TOR1AIP1, ESR1, EGFR, STAT1, miR-192, GATA3, COL1A1, in tumor microenvironment generic network." (PMID 33907495, 2021).
tumor (continued). "Actually, phosphorylated STAT1 and STAT3 dimer in tumor cytosol can bind to the PD-L1 promoter to induce PD-L1 expression while inhibition of STAT3 activity by STATTIC mitigates the CXCR3 activation-induced PD-L1 expression in tumor cells." (PMID 33407095, 2021). "Clearly, results from both assays agreed with each other in that human STAT1 was strongly detected in the tumor part of OC3 tissue sections, whereas mouse STAT1 was more evident in the stroma parts of TW2.6 tissue sections." (PMID 32605311, 2020). "At the same time, STAT1 signal triggering can activate T cells and induce apoptosis of PD1-sensitive tumor cells." (PMID 32294625, 2020). "A huge impact arose on the STAT1 signaling pathway in knockdown of USP22, which will change the developmental process of tumor cells." (PMID 32294625, 2020). "Stat1-positive and Stat1-negative RT2-cancers expressed PD-L1 in the tumour tissue and on more than 10% of the isolated cancer cells, showing that Stat1-negative RT2-cancers expressed the target of the anti-PD-L1 mAb." (PMID 32165639, 2020). "Thus, BHLHE40-mediated tumor suppression can be traced to inhibition of oncogenic factors such as STAT1, whereas BHLHE40-mediated promotion of tumor progression may be traced to the activation of the PI3K/Akt/mTOR pathway and the upregulation of pro-survival factors such as survivin and clusterin." (PMID 32577154, 2020). "In summary, we point out the role of IFNβ activated Stat1/Stat2/IRF9 signalling in cancer invasion plasticity, aside from its known role as a tumour suppressor." (PMID 32872349, 2020). "The expression of PD-L1 was induced by EGFR and JAK2/STAT1, while the inhibition of JAK2 repressed the upregulation of PD-L1 in tumor cells and enhanced their immunogenicity." (PMID 33603661, 2020). "One of the mechanisms for tumor cell-stimulated expression of PD-L1 is the activation of the EGFR, ERK1/2, PI3K-Akt, or Janus kinase 2/STAT1 signaling pathways." (PMID 32756527, 2020). "Interleukin (IL)-1β and interferon gamma (IFNγ) activate STAT1 to produce ARG1 and inducible nitric oxide synthase (iNOS) and suppressive cytokines such as TGFβ to play a role in promoting tumor growth." (PMID 32325683, 2020). "IHC examination of the tumor xenografts eluted that the STAT1 and PD-L1 were enhanced in PSMB8-AS1 overexpressed group xenografts, whereas STAT1 and PD-L1 were markedly suppressed in the PSMB8-AS1 downregulated group." (PMID 32891166, 2020). "These cytokines then reciprocally activate the signal transducer and activator of transcription 1 (STAT1) and NF-κB pathways in the tumor cells, ensuring the proliferation of the metastatic cells." (PMID 33321749, 2020). "The other cluster including RASSF5, RASSF6, STAT1, CEACAM1, BNIP3L and SOCS2 is related to tumor suppression." (PMID 32201535, 2020). "More and more studies show that STAT1 mediated IFN signal is a key step in monitoring the immune system to recognize and eradicate emerging tumor." (PMID 32294625, 2020). "TB11-Fhit-transfected tumor cells showed a significant increase in the expression of IRF-1, Jak1, Ptpsh1, Stat1, Stat2, and Stat3 genes." (PMID 32545680, 2020). "A similar pattern of tumor growth was seen upon injection of RMA-S cells, which grew to significantly bigger tumors in Stat1–/– and Stat1β/β mice compared to Stat1α/α and WT mice, albeit tumors were smaller in Stat1β/β than in Stat1–/– mice." (PMID 33042133, 2020). "However, a growing number of reports suggest that STAT1 could have tumor promoting activities." (PMID 31992798, 2020). "We identified a tumor cell specific, STAT1-centered, immune signature expressed by the MSI-H tumor cells." (PMID 32641473, 2020). "Other studies have demonstrated that STAT1 activation is upregulated in M1 macrophages and is correlated with developing antitumor responses, while STAT3 is considered an oncogene promoting tumor growth." (PMID 33036138, 2020).
tumor (continued). "In the same manner, miR-145 exhibits a tumor suppressor activity in CRC by modulating Myc, STAT1 and other genes including IRS-1.In fact, miR-145 downregulation was shown to increase tumor survival, a feature sharply in contrast with the therapeutic success." (PMID 33396628, 2020). "Because miRNAs can act either as tumor suppressors or oncogenes, depending on their target genes in different recipient cells, we identified three anti-angiogenesis genes (THBS1, STAT1, LIF) as target gene of miR-194." (PMID 31700002, 2019). "A subset of ISGs with pro-apoptotic and anti-proliferative functions have been identified to be stimulated by STAT1 during IFN treatment, through which regulate tumor growth." (PMID 30456450, 2019). "Among a total of 6 tumor cell lines assessed, which all showed reduction of IFN-g-induced PD-L1 expression after STAT1 knockdown, three also showed reduction of IFN-g-induced HLA-DR expression, regardless of baseline HLA-DR expression (e.g., JHU-022)." (PMID 31730010, 2019). "When the tumor cells were cultured under OGD conditions, the upregulation of total STAT1 protein expression was inhibited, corroborating the qPCR results." (PMID 31196219, 2019). "For instance, STAT1 can enhance IFN-γ production and the cytotoxicity of NK cells; phosphorylated STAT3 can impair tumour immune surveillance and promote tumour escape from immune control." (PMID 31324197, 2019). "SRC-1 also interacts with STAT1, STAT3, STAT5 and STAT6, and although STAT3 and STAT5 are considered as tumorigenic transcription factors, STAT1 is a tumor suppressor." (PMID 31178825, 2019). "The presence of FGL2 in tumor cells inhibited granulocyte-macrophage colony-stimulating factor (GM-CSF)-induced CD103+ DC differentiation by suppressing NF-κB, STAT1/5, and p38 activation." (PMID 30683885, 2019). "The upregulation of activated STAT1 in the acquired resistance model can be interpreted as a possible immune escape mechanism of the tumor cells to upregulate PDL-1 and evade the CD8+ tumor infiltrating lymphocytes." (PMID 31323891, 2019). "Strikingly, we observed that knockout of u-STAT1 inhibited CFU formation of HCC cells, in contrast to previous findings that STAT1 served as a tumor suppressor." (PMID 30456450, 2019). "To further explore the potential roles of STAT1 and STAT3 in IFN-g-induced PD-L1 expression on tumor cells, we knocked down their expression with specific siRNAs." (PMID 31730010, 2019). "Strikingly, IFNy-mediated upregulation of Stat1 expression levels were significantly inhibited in both TC1 and B16F10 tumor cells under OGD conditions." (PMID 31196219, 2019). "Conversely, restoring IFN-β expression in OSM-expressing TNBC cells restored the expression of select ISGs (including STAT1, STAT2, IRF9, SOCS1, MX1, and OAS1 and reduced tumor sphere formation and tumor-initiating capacity." (PMID 31036052, 2019). "Similar to our findings in tumor cell lines, IFN-g preferentially activated STAT1 in Monos, while IL-27 activated both STAT1 and STAT3; IL-10 preferentially activated STAT3." (PMID 31730010, 2019). "In other tumor samples or experimental tissue culture settings, STAT3 only, or other dual combinations of activated STAT1/3/5, are described." (PMID 31694222, 2019). "In responders to IMiDs, IMiDs are able to stimulate immune effector cells to enhance IFN-γ production in an ambient tumor microenvironment, which can stimulate the IFN-γ-STAT1 pathway in MM cells." (PMID 30956773, 2019). "Other candidates such as EGR1, RUNX2, STAT1, TRAP2, IRF1 and USF1 have been experimentally validated as drug targets, metastasis promoter or tumor growth enhancers, see19–24." (PMID 31857653, 2019). "Here, the authors show that FGL-2 expressed by GBM cancer cells acts by suppressing the differentiation of CD103+ DC cells required to activate the anti-tumor CD8+ T cell response via blocking GM-CSF signalling at NFKB, STAT1/5 and p38 level." (PMID 30683885, 2019).
tumor (continued). "Hypothetically, the IFN-γ-STAT1 signaling induces apoptosis in proliferating tumor cells; however, TRCs-induced overexpression of IDO1 and AhR, shifts IFN-γ action and give rise to IDO1/AhR-induced p27 activation and inhibition of STAT1 signaling." (PMID 31430951, 2019). "We furthermore show that TYK2 is activated by an autocrine loop involving IL-10 and IL-22 and that STAT1 and STAT3 are essential mediators of aberrant tumor cell survival through activation of the pro-survival protein MCL1." (PMID 30131584, 2019). "PGE2 binds to EP1 and activates the EP1 signaling pathway, which in turn promotes tumor expression of ANGPTL4 and cANGPTL4 via activation on transcriptional activator (STAT) 1 (STAT1)." (PMID 30049845, 2018). "In an immune stimulatory tumour microenvironment, eosinophils would produce high numbers of potent chemoattractants for CD8+T cells via STAT1, such as CCL5, CXCL10, CXCL1118." (PMID 29440650, 2018). "In the present study, we found that overexpression of PLAC2 blocked tumour cell proliferation and cell cycle progression in vitro and tumorigenesis in vivo by decreasing the level of RPL36 via interaction with STAT1." (PMID 28922548, 2018). "Consistent with this possibility, a study carried out on resistant SCCs concluded that STAT1 is overexpressed in tumors adapted to continuous exposure to IFN, leading to the selection of tumor clones resistant to IFN-mediated cytotoxicity and RT effects." (PMID 30186768, 2018). "Thus, STAT1 appears to be necessary to recruit Ly6Chi “inflammatory monocytes” early on in CAC development which may transform into effector M1 cells with cytotoxic activity in the tumor microenvironment." (PMID 30235866, 2018). "Consistently, CD44, OAS3, ISG15, STAT1, and WNT5A were significantly upregulated whereas KIT was significantly downregulated in tumor compared to normal in GSE13861." (PMID 30134903, 2018). "There is increasing evidence suggesting that mouse double minute 2 homolog (MDM2), insulin-like growth factor 1 (IGF1), signal transducer and activator of transcription 1 (STAT1), and Rac family small GTPase 1 (RAC1) are involved in tumor progression." (PMID 29651441, 2018). "Signal transducer and activator of transcription-1 (STAT1), a member of the STAT family, is a tumor suppressor, preventing development and progression of established tumors." (PMID 28903386, 2017). "In gene level, oncogenic signaling pathways in tumor cells, such as IFN-γ/JAK2/IFN, ALK/STAT3, PI3K, and MEK/ERK/STAT1 can activate PD-L1 expression." (PMID 27974689, 2017). "The up-regulation of STAT1 in our study by treatment with MG, alone or combination with GLOI silencing, is interesting because STAT1 is a known tumor suppressor." (PMID 28903386, 2017). "When the expression of NRCP was silenced by the introduction of siRNA–NRCP into the tumor microenvironment, binding of RNA polymerase II to STAT1 decreased, indicating that NRCP acts as an intermediate in the binding of STAT1-RNA polymerase II." (PMID 28738810, 2017). "This activation leads to phosphorylation of STAT1, STAT3, STAT5, ERK1/2, AKT and mTOR and goes on to drive EMT and promote invasion, migration, and proliferation for tumor progression." (PMID 28223541, 2017). "Interestingly, we also detected alterations in the expression of STAT1 and proteosomal proteins; however, we found very low levels of STAT1 and decreased proteosomal proteins (PSME1/2) in the Inf/FMX variant which is associated with a high incidence of tumor recurrence and nodal metastasis." (PMID 29225558, 2017). "We next injected these cells into the mammary fat pads of CD8+/+ or CD8−/− mice, to examine the functional significance of STAT1 and STAT3 in modulating the balance between pro- versus anti-tumour immunity." (PMID 28276425, 2017). "Several of these genes, including IFI27, IFITM1, IRF1, STAT1, IF16, and TAP1, are known to possess potent anti-proliferative and tumor suppressive properties." (PMID 29176033, 2017).
tumor (continued). "Interestingly, another recent study showed that bortezomib could inhibit the downstream signaling of indoleamine 2,3-dioxygenase, a major inducer of immune tolerance during tumor development, through suppression of signal transducer and activator of transcription 1 (STAT1) in NPC cells." (PMID 29160853, 2017). "Our observations suggest that Stat1-null LOP cells, combined with the age-related changes in the tumor microenvironment, contribute to the development of a malignant neoplasm." (PMID 28865492, 2017). "The relationship between ph-STAT1 and ph-STAT3 tumour cell expression and CSS using Kaplan-Meier log rank test, with relevance to different molecular subtypes, was examined." (PMID 27769057, 2016). "The IHC staining of total and ph-STAT1 and STAT3 was homogenous in both the cytoplasm and nuclei of tumour cells, which is consistent with previous reports." (PMID 27769057, 2016). "Tumour cell expression of STAT1 and STAT3 at both cytoplasmic and nuclear locations were combined and identified as STAT1/STAT3 tumour cell expression." (PMID 27769057, 2016). "In the present study, the prognostic role of ph-STAT1 and ph-STAT3 tumour cell expression in different molecular subtypes was examined." (PMID 27769057, 2016). "In conclusion, STAT1 and STAT3 tumour cell expression appears to be an important determinant of favourable outcome in patients with invasive ductal breast cancer." (PMID 27769057, 2016). "STAT1 and STAT3 have a complex interaction with both tumour cells and the tumour microenvironment including immune infiltrates such that STAT1 and STAT3 are thought to play opposite roles in tumorigenesis, regulating distinct gene signatures." (PMID 27769057, 2016). "It is plausible that STAT1 and STAT3 have prognostic value in different tumour types, different molecular subtypes or in different aspects of the tumour microenvironment." (PMID 27769057, 2016). "Taken together, the results of the present study would suggest that both STAT1 and STAT3 act as tumour-suppressor proteins in patients with ductal breast cancer." (PMID 27769057, 2016). "In contrast, depletion of STAT3 in HT-29 and LS174T (high STAT1+low STAT3) resulted in growth reduction, as assessed by tumor growth curves and tumor weight at end point analysis." (PMID 27191495, 2016). "Total and ph-STAT1 and STAT3 expression in tumour cells were quantified using the weighted histoscore, taking the staining intensity and percentage into account." (PMID 27769057, 2016). "It has been previously suggested that the mutual interdependence of STAT1 and STAT3 through heterodimer formation on the chromatin of tumor cells has a crucial influence on cancer cell fate." (PMID 27191495, 2016). "STAT1 and STAT3 tumour cell expression appeared to be an important determinant of favourable outcome in patients with invasive ductal breast cancer." (PMID 27769057, 2016). "Expression of the miR203 target genes, STAT1, PI3KCA and IVNS1ABP, was markedly inhibited in tumor extracts from mice injected with enforced miR203 expressing cells as determined by qPCR, and immunoblotting." (PMID 27705947, 2016). "Overall, STAT1 induces anti-proliferative and pro-apoptotic genes such as caspases 3, 6, 8, FAS/FASL, p21waf1, c-myc that directly hamper tumour growth." (PMID 25705130, 2015). "In the case of the mutant PDGFRα proteins, we observe a strong and long lasting activation of STAT1, STAT3 and STAT5, which will undoubtedly have a much more prominent effect on the cells and/or the tumour microenvironment." (PMID 25880691, 2015). "Perforin-1, IFN-γ, STAT-1 and T cells each contribute to reducing 3-MCA-induced tumor formation and growth." (PMID 26555296, 2015). "As expected, the expression levels of STAT1 and MX1 were up-regulated in OSCC tumors (7/9 and 9/9 for STAT1 and MX1, respectively), whereas the levels of ANXA2 were similar between the tumor tissues and the adjacent normal tissues." (PMID 26110569, 2015).